ATP6V1D (ATPase H+ transporting V1 subunit D)
Description:
Subunit of the V1 complex of vacuolar(H+)-ATPase (V-ATPase), a multisubunit enzyme composed of a peripheral complex (V1) that hydrolyzes ATP and a membrane integral complex (V0) that translocates protons. V-ATPase is responsible for acidifying and maintaining the pH of intracellular compartments and in some cell types, is targeted to the plasma membrane, where it promotes acidification of the extracellular environment (By similarity). The V-ATPase complex also acts as an activator for mTORC1 on lysosomal membrane by promoting the guanine nucleotide exchange factor (GEF) of the Ragulator complex, thereby enabling mTORC1 recruitment. May play a role in cilium biogenesis through regulation of the transport and the localization of proteins to the cilium.
Synonyms: ATP6M; VATD; VMA8
Tractability: Small molecule: a structure with a bound ligand is known. Antibody: UniProt places it where antibodies can reach, with high confidence; its Gene Ontology location is reachable by antibodies, with high confidence. PROTAC: ubiquitination databases record sites on it; its protein half-life has been measured.
Gene: Protein-coding gene on chromosome 14 (67,294,371 to 67,360,265, reverse strand). Ensembl gene ENSG00000100554.
Subcellular location: Membrane; Cytoplasmic vesicle, clathrin- coated vesicle membrane; Lysosome membrane; Cytoplasm, cytoskeleton, microtubule organizing center, centrosome; Cell projection, cilium
Subcellular location (Human Protein Atlas): Plasma membrane; Nucleoplasm
Pathways (Reactome):
Immune System: Neutrophil degranulation; ROS and RNS production in phagocytes
Transport of small molecules: Ion channel transport; Transferrin endocytosis and recycling
Cellular responses to stimuli: Amino acids regulate mTORC1
Developmental Biology: Regulation of MITF-M-dependent genes involved in lysosome biogenesis and autophagy
Signal Transduction: Insulin receptor recycling
Gene Ontology:
Molecular function: guanyl nucleotide exchange factor activator activity; protein binding; proton-transporting ATPase activity, rotational mechanism; proton transmembrane transporter activity
Biological process: cellular response to amino acid stimulus; cilium assembly; positive regulation of TORC1 signaling; protein localization to cilium; endosomal lumen acidification; Golgi lumen acidification; intracellular pH reduction; lysosomal lumen acidification; proton transmembrane transport; regulation of macroautophagy; vacuolar acidification; synaptic vesicle lumen acidification
Cellular component: centrosome; cilium; extracellular exosome; lysosomal membrane; lysosomal proton-transporting V-type ATPase complex; membrane; plasma membrane; proton-transporting V-type ATPase complex; cytosol; endosome membrane; Golgi membrane; specific granule membrane; vacuolar proton-transporting V-type ATPase, V1 domain; clathrin-coated vesicle membrane; extrinsic component of synaptic vesicle membrane
Genetic constraint (gnomAD): Loss-of-function variants: 19 observed, 33.65 expected, observed/expected ratio (o/e) 0.56, 90% interval 0.39 to 0.83. The upper end of that interval is the gene's LOEUF score, 0.83, which puts it in group 3 of 6, group 1 being the genes least tolerant of losing a copy. Missense variants: 199 observed, 270.76 expected, observed/expected ratio (o/e) 0.73, 90% interval 0.65 to 0.83. Synonymous variants: 88 observed, 96.84 expected, observed/expected ratio (o/e) 0.91, 90% interval 0.76 to 1.09.
Homologues: Orthologues: chimpanzee ATP6V1D (100% identical), macaque ATP6V1D (100% identical), dog ATP6V1D (99% identical), guinea pig ATP6V1D (99% identical), rat Atp6v1d (99% identical), mouse Atp6v1d (98% identical), rabbit ATP6V1D (95% identical), pig ATP6V1D (95% identical), tropical clawed frog atp6v1d (89% identical), zebrafish atp6v1d (88% identical), Drosophila melanogaster Vha36-1 (72% identical), Caenorhabditis elegans vha-14 (70% identical), and 1 more.
Diseases named in the same sentence as ATP6V1D in open-access papers:
ATP6V1D is named in the same sentence as 14 diseases in open-access papers, as found by Europe PMC text mining. Sharing a sentence is not in itself a finding about the gene and the disease. The quoted sentences say what the papers report.
diabetes (1 paper, 2019). "Among the top 10 positive differentially hubbed genes is the ATP6V0E gene, from the same family of ATP6V1D gene, which has been reported as a factor mediating hepatic steatosis, a metabolic syndrome frequently associated with obesity and diabetes." (PMID 31354792, 2019).
ovarian carcinoma (1 paper, 2024). A malignant neoplasm originating from the surface ovarian epithelium. "We also found that the combination of MTF and SIM synergistically suppressed the expression of ATP6V1D in ovarian cancer cells." (PMID 38489280, 2024).
Paget's disease of the bone (1 paper, 2022). "Tiludronic acid (DB01133), an inhibitor of ATP6V1D, ATP6V1G2, and ATP6V1H, is used for the treatment of Paget's disease of the bone." (PMID 35875800, 2022).
brain disease (1 paper, 2015). "Moreover, 10 genes (ATP1A1, ATP6V1D, C16orf45, CROCC, KLC1, LUC7L2, PIAS2, PRKAR1B, RBFOX1, and RPL19) interacts with at least one brain disease-associated gene." (PMID 26043779, 2015).
infection (1 paper, 2026). The state of being infected such as from the introduction of a foreign agent such as serum, vaccine, antigenic substance or organism. "gondii-resistant rat (Lewis) and identified small GTPase immunity-associated proteins (GIMAPs), and lysosome-associated proteins (including ATP6V1D) that are upregulated in response to infection." (PMID 41972776, 2026).
tumor (1 paper, 2020). "The results showed that the mRNA expressions of ATP6V1D, ATP6V1F, and ATP6V1F were obviously related to tumor purity." (PMID 33194650, 2020).
ATP6V1D also shares sentences with these, for which no sentence is quoted: cancer (1 paper); Cirrhosis (1); cognitive decline (1); Hepatic steatosis (1); memory impairment (1); metabolic syndrome (1); Obesity (1); prostate carcinoma (1).